CDK4 (cyclin dependent kinase 4)
Diseases named in the same sentence as CDK4 in open-access papers (continued):
Sharing a sentence is not in itself a finding about the gene and the disease.
cancer (continued). "Firstly, although we show that the increase of ROS by the combination of CDK4/6i and PARPi is the dominant mechanism to synergistically inhibit RB-deficient cancer cells, we cannot exclude other mechanisms that may also cooperate or contribute to this synergistic effect." (PMID 32249776, 2020). "In addition, CDK4 mutations have been reported in several types of cancer." (PMID 27708221, 2016). "In contrast, loss of Cdh1 was recently shown to bypass the dependency of cancer cells on Cdk4/6, indicating that Cdh1 loss may constitute an exclusion criterion for treatment with the recently developed Cdk4/6 inhibitors, or could be a mechanism of acquired resistance to such drugs." (PMID 26650195, 2016). "Thus, because the abnormal function of the CDK4-cyclin D1 protein complex might play a vital role in causing cancer, CDK4 can be considered a genetically validated therapeutic target." (PMID 26252490, 2015). "Indeed, inositol hexaphosphate has also been reported to decrease Cdk4 and cyclin D1 protein expression levels in addition to the inhibition of Rb phosphorylation at Ser780, Ser807, and Ser811, causing G1 arrest and apoptotic death of human cancers." (PMID 25255129, 2014). "CDK4/6 inhibitors target the CDK4/6 complex, thereby promoting the activation of retinoblastoma protein, which hinders cancer cells from entering the G1 checkpoint to the S phase of the cell cycle." (PMID 41141392, 2026). "The nanostructure achieved high loading capacity (81.25%) for the CDK4/6 inhibitor palbociclib and enabled efficient in vitro delivery, improving selectivity toward cancer cells." (PMID 42095698, 2026). "One of the most prominent milestones in the approach to targeting the cancer cell cycle was the development and approval of CDK4/6 inhibitors such as palbociclib, ribociclib, and abemaciclib." (PMID 41595248, 2026). "Using a translationally relevant 3D vascularized microfluidic system, we provide evidence that early CDK4/6 inhibition not only stall cancer cell growth but also promotes immune cells recruitment." (PMID 42215475, 2026). "Thereby, we propose a rational combination strategy of employing CDK4 inhibitors with immune checkpoint blockers (ICBs) to overcome ZDHHC17-driven cancers." (PMID 42133178, 2026). "In carcinoma models, CDK4/6 and PD-1 inhibition induce intratumoral inflammation and synergistic activity." (PMID 41325133, 2026). "Upon light irradiation, Opto-PROTAC can be cleaved to release free PROTAC, inducing the ubiquitination and proteasomal degradation of CDK4/6 and G1 cell-cycle arrest for enhanced specificity in cancer therapy." (PMID 40894871, 2025). "Through gene set enrichment analysis (GSEA), we discovered that TMEM45A promotes cancer cells resistance to CDK4/6i and glycolysis by activating the AKT/mTOR signaling pathway." (PMID 39910045, 2025). "Many cancer types are dependent on these activities for growth, and small molecule CDK4/6 inhibitors are widely studied in clinical trials or have shown success in the treatment of some cancer types." (PMID 40210435, 2025). "CDK4/6 inhibitors have been proposed for use in combination therapy with a CDK2 inhibitor to prevent compensatory upregulation of CDK4/6 activity, allowing cancer cells to bypass the G1/S checkpoint." (PMID 40232858, 2025). "The finding that CDK4/6 activity promotes origin licensing also has ramifications for cancer medicine." (PMID 40940326, 2025). "Targeting cell cycle through cyclin-dependent kinases 4 and 6 (CDK4/6) inhibition (CDK4/6i) is an established strategy in the treatment of several cancer types." (PMID 40696167, 2025). "Exogenous IL-15 improves CDK4/6 inhibitor efficacy by augmenting T-cell proliferation and cancer cell killing by T cells." (PMID 40032842, 2025).
cancer (continued). "The ExCy and Fujifilm’s mRNA transcripts in the Disease pathway were revealed by TCGA’s Cancer Gene Consensus analysis to be more likely mutated: MUC4, CDK4, and CD79A, ARAF, respectively." (PMID 40598203, 2025). "Cancer progression is characterized by dysregulated G1/S phase transition mediated by CDK4/6-dependent Rb protein phosphorylation." (PMID 40894871, 2025). "Currently, five CDK4/6 inhibitors (CDK4/6is), palbociclib, ribociclib, abemaciclib, dalpiciclib, and trilaciclib, have been approved for use in the clinical treatment of cancer." (PMID 41463246, 2025). "Many marine-derived compounds exhibit potent anti-proliferative effects, making them promising candidates for cancer therapy, including as potential CDK4/6 inhibitors." (PMID 39813224, 2025). "Biomarkers of response will be critical for further development of CDK4/6 inhibitors in gastrointestinal and other cancers." (PMID 40699853, 2025). "Mechanistically, the up-regulation of MHC molecules on the cancer cell surface upon treatment with CDK4/6 inhibitors was correlated with the immune surveillance-promoting effects of the interferon signalling." (PMID 41388212, 2025). "The development of CDK4/6 inhibitors represents a key milestone in cancer therapeutics, demonstrating improved overall survival with manageable toxicities." (PMID 40856900, 2025). "The sustained activation of CDK4/6 is thought to occur in most cancers as a mechanism to promote continuous transition from the G1 to the S phase." (PMID 40864763, 2025). "The cyclin D/CDK4 complex has become a promising target in cancer therapy, and our computational analysis highlights the potential of compound C2 as an inhibitor of this complex." (PMID 40845025, 2025). "These cell lines were selected to reflect the post-treatment cancer cells resistant to endocrine +/− CDK4/6i therapy experienced during the FELINE trial." (PMID 40341770, 2025). "Collectively, these findings suggested that CDK4 inhibition-induced epigenetic modifications activated c-Myc-target genes, ultimately promoting cell cycle maintenance in cancer cells." (PMID 41161384, 2025). "Regarding CDK4/6 inhibitors, somatic mutations in CDK 4 inhibitor B (CDKN2B) were associated with an increased risk of cancer-associated VTE, suggesting a potential pathophysiological link between CDK4/6-inhibiton and thrombotic risk." (PMID 40896464, 2025). "The concept of myeloid protection through CDK4/6 inhibition holds significant importance in cancer therapy, as chemotherapy remains a cornerstone in the treatment of many cancers, and its myelosuppressive effects often compromise therapeutic outcomes." (PMID 40478388, 2025). "In this phase I/II study, abemaciclib will be given prior to Lu-PSMA-617 to evaluate if the CDK4/6 is able to upregulate prostate-specific membrane antigen (PSMA) expression in the cancer cells and, as such, potentiate the effects of Lu-PSMA-617." (PMID 40075623, 2025). "The concurrent inhibition of RTKs and CDK4/6 has exhibited a synergistic lethality in the context of cancer therapy." (PMID 40563591, 2025). "By contrast, there have been multiple preclinical studies evaluating the efficacy of a CDK4/6 inhibitor in combination with a MEK inhibitor in other types of cancer." (PMID 41428766, 2025). "This light-controlled system allows spatiotemporal CDK4/6 degradation and G1 cell-cycle arrest, providing a promising strategy to enhance specificity for cancer treatment and fundamental biological research." (PMID 40894871, 2025). "Although CDK inhibitors targeting Cyclin D1/CDK4/6 complexes have shown therapeutic potential in cancers such as breast and lung, their role in EC remains underexplored." (PMID 39940659, 2025). "CDKs play key roles in cancer progression, making them important targets for cancer therapy, as evidenced by several approved CDK4/6 inhibitors in breast and lung cancer and ongoing clinical trials in other tumor types." (PMID 40075638, 2025).
cancer (continued). "The CDK4/6-RB axis thus links replication licensing to proliferation, which has implications for human cell fate control and cancer therapy design." (PMID 40940326, 2025). "Preclinical studies evaluating CDK4/6 inhibitors suggest synergy with chemotherapy for several cancer types." (PMID 40864763, 2025). "This review discusses the mechanisms by which CDK4/6 inhibitors combat cancer cells and highlights recent advancements in combination therapies." (PMID 40563591, 2025). "Gankyrin also regulates the cell cycle by interacting with the cyclin-dependent kinases 4 (CDK4) and MDM2 which are both involved in tumor suppression and have been found mutated in many cancers." (PMID 40771905, 2025). "Cancer cells, identified by the expression of Ctnnb1 and Cdk4, were further stratified into four subtypes (cancer cells 1–4)." (PMID 40723284, 2025). "In this real-world study, we looked at the use of two oral drugs, everolimus and exemestane, in women whose cancer had already progressed after modern treatments like CDK4/6 inhibitors and chemotherapy." (PMID 41002573, 2025). "Cancer cells resistant to CDK4/6 inhibitors exhibit significant differences from sensitive cells at the genomic, transcriptomic, and proteomic levels." (PMID 40563591, 2025). "Our results demonstrated that these adaptations render cancer cells that survive CDK4/6 inhibition highly sensitive to MYC, glutaminase (GLS1), or mTOR inhibitors and hypoxic conditions." (PMID 40696167, 2025). "We then used long-term experimental evolution of each cell line under ribociclib to develop three paired cancer cell lines with joint endocrine and CDK4/6i resistance (evolved lines with combination ribociclib resistance (CRR))." (PMID 40341770, 2025). "A recent study has shown that blocking autophagy can re-sensitise cancer cells to CDK4/6 inhibitors." (PMID 40563591, 2025). "In HPV− cancers, mutations in the CDKN2A gene frequently lead to the absence or dysfunction of the p16 protein, which disinhibits the cyclin D1/CDK4/6 complex." (PMID 40940964, 2025). "Metabolic flexibility, which is required for the response to metabolic challenges in cancer, was compromised in CDK4-KO TNBC cells (Sup." (PMID 39788939, 2025). "Previous studies have shown that inhibition of BCL-2 and CDK4/6 combined with endocrine therapy can inhibit proliferation and induce apoptosis of cancer cells, including phenotype senescent cells, thereby enhancing reactivity in vivo." (PMID 40104496, 2025). "To better understand the impact of CDK4/6 inhibitors in a real-world setting, we conducted a retrospective study at a cancer center in Romania." (PMID 40244189, 2025). "Among 119 listed trials the vast majority is testing different CDK4/6 inhibitors in different type of cancer alone or in combination therapies." (PMID 39800748, 2025). "The combination of renin-angiotensin system inhibitors with cyclin-dependent kinase 4/6 inhibitors is an emerging area of interest in cancer research." (PMID 41417371, 2025). "Different cyclins share functional similarities in activating CDK4/6, and cyclin D1 is more frequently dysregulated in human cancers." (PMID 40563591, 2025). "The overexpression of cyclin D or CDK4/6 is observed in several cancers, making CDK4/6 inhibitors an attractive therapeutic option." (PMID 40740243, 2025). "CDK4/6 inhibition represents a new generation of cancer therapies, targeting CDK4/6 complexes to induce cell cycle arrest in the G1 phase." (PMID 40563591, 2025). "We report RBness as a pan-cancer phenomenon, associated with patient outcome and chemotherapy response in multiple cancer types, and predictive of CDK4/6 inhibitor response in estrogen-positive breast cancer." (PMID 40138429, 2025). "The top cancer genes with recurrent variants included: STAT2 (33%), DMNT1 (27%), HSP90AA1 (17%), CDK4, NOTCH2, THRAP3, and SALL4 (13% each)." (PMID 41353477, 2025).
cancer (continued). "Collectively, these results highlight an intricate programme governed by TCF1/Wnt signalling which activates ERK/CDK4/6, thus integrating cancer stemness with self-renewal and inhibition of differentiation." (PMID 40764669, 2025). "MS28 demonstrated a faster and more effective degradation of cyclin D1 compared to CDK4/6, with notable effects on cancer cell proliferation, outperforming traditional CDK4/6 inhibitors." (PMID 40793752, 2025). "To further evaluate the effectiveness and potential adverse events of different types of CDK4/6 inhibitors in the treatment of malignant tumors, we performed a meta-analysis by aggregating data from multiple randomized controlled trials." (PMID 40104496, 2025). "CDK4/6-mediated Rb phosphorylation and G1/S phase transition play critical roles in cancer cell proliferation." (PMID 40894871, 2025). "Targeting the cell cycle has become a focus of cancer research bearing impressive results with the introduction of CDK4/6 inhibitors in the treatment of ER-positive/HER2-negative breast cancers." (PMID 40699853, 2025). "The increased sensitivity of BRG1-LOF tumors to degraders or inhibitors of SMARCA2, aurora kinase, CDK4/6, oxidative phosphorylation, and other survival factors demonstrates the broad therapeutic vulnerabilities of these cancers." (PMID 41008934, 2025). "Novel anti-HER2 ADCs with structural innovations are being developed, and combinations of anti-HER2 ADCs with other types of anti-cancer agents such as immune checkpoint inhibitors, tyrosine kinase inhibitors, or CDK4/6 inhibitors are also being investigated." (PMID 39837059, 2025). "Beyond conventional therapeutic combinations, emerging insights into CDK4/6 inhibitor-induced epigenetic reprogramming of cancer cells have spurred interest in leveraging this mechanism for synergistic therapeutic strategies." (PMID 40421216, 2025). "Dysregulation of CDK4, commonly observed in cancer, contributes to uncontrolled cell growth, making it a prime target for cancer treatment strategies, especially those focused on inhibiting cell proliferation." (PMID 40740783, 2025). "Through in vitro coculture experiments, we discover the immune-suppressive effects of CDK4/6 inhibition and demonstrate that enhancing T cell activating communications can overcome this, reinvigorating cancer cell response to cycle therapy." (PMID 40032842, 2025). "By activating the mTOR signaling pathway, cancer cells can continue to support cell survival and proliferation, circumventing the inhibitory effects of CDK4/6 inhibitors." (PMID 40303296, 2025). "CDK4/6 inhibition and estrogen receptor (ER) antagonist therapy demonstrate strong synergistic effects in cancer treatment." (PMID 40563591, 2025). "This distinction is particularly relevant to CDK4/6 inhibitor-resistant cancer cells, as well as in adult tissues and HSCs." (PMID 40093074, 2025). "It contributes to cancer cell proliferation by assisting in the folding of Cyclin D1 and supporting the formation of the Cyclin D1/CDK4 holoenzyme complex, which triggers cancer cell proliferation." (PMID 40214463, 2025). "A more recent approach to improving the antitumor efficacy of CDK4/6is in cancer focused on the functional redundancies in the Cyclin–CDK circuitry." (PMID 40282469, 2025). "The PI3K-AKT-mTOR and CDK4/6-Rb pathways are two critical regulators of cell cycle progression and cancer proliferation." (PMID 40563591, 2025). "CDK4/6 inhibitors are essential for preventing cancer cell growth by blocking the activity of cyclin-dependent kinases 4 and 6, particularly in the treatment of advanced ER+ and HER2-negative breast cancer." (PMID 40303296, 2025).
cancer (continued). "In summary, current pre-clinical research demonstrates the significant potential of combining CDK4/6 inhibition with immune checkpoint inhibition in cancer treatment." (PMID 40563591, 2025). "Given their crucial role in cell proliferation, CDK4/6 s have emerged as promising therapeutic targets in cancer treatment." (PMID 40836337, 2025). "Cyclin-dependent kinase 4 (CDK4) plays a pivotal role in cell cycle regulation and is a well-established target in cancer therapy." (PMID 41176773, 2025). "A significant mean decline in Ki-67 expression was observed at two weeks, a finding that encouraged further exploration of CDK4/6 inhibition in HER2+ cancers." (PMID 40940886, 2025). "To uncover the compensatory GF signal-mediated proliferation phenotype of these endocrine + CDK4/6i-resistant cancer cells, we profiled tumors of a much larger cohort of patients (the discovery and validation cohorts)." (PMID 40341770, 2025). "For instance, some marine-derived alkaloids and terpenes have shown promising results in initial screenings, demonstrating the ability to modulate CDK4/6 activity and induce cell cycle arrest in cancer cell lines." (PMID 39813224, 2025). "In many cancers, including OS, CDK4 is frequently overexpressed or amplified, contributing to aberrant cell cycle progression." (PMID 40076599, 2025). "Together, these results suggest that preventing DNA DSBs repair by NEK6 inhibition enhances the vulnerability of cancer cells to CDK4/6 inhibition." (PMID 41560755, 2025). "CDK4/6 inhibitors block the G1 to S phase transition in cancer cells, and selective CDK4/6 inhibitors such as Palbociclib and Ribociclib have been approved by EMA and FDA for treating ER-negative metastatic BC." (PMID 40573134, 2025). "Extensive research about both the mechanism of action and resistance to CDK4/6 inhibitors has been conducted in the last years since this vulnerability of cancer cells was discovered." (PMID 39860516, 2025). "Metabolism alterations enhance the adaptability of cancer cells, allowing them to survive in the presence of the CDK4/6 inhibitors, thereby promoting the development of drug resistance." (PMID 40563591, 2025). "Beyond the recurrent amplification of CCND1, CCND2, CDK4, MDM2, and MYCL1, chromothriptic chromosomes were associated with the amplification or loss of other well-established cancer genes." (PMID 39185963, 2025). "PROTAC‐based degraders targeting CDK4 offer a promising strategy for cancer treatment, potentially overcoming acquired resistance associated with traditional CDK4/6 inhibitors such as palbociclib." (PMID 41026144, 2025). "This review provides a comprehensive overview of the mechanisms by which CDK4/6 inhibitors combat cancer and explores their potential for more effective and personalized treatment strategies." (PMID 40563591, 2025). "This study suggests that the combination of BCL2 inhibitors and CDK4/6 inhibitors is a promising double-hit anti-cancer strategy." (PMID 40563591, 2025). "Despite the clinical success of targeted therapies against CDK4/6 and other cancer dependencies, treatment resistance is a universal obstacle to achieving durable remission and patient survival." (PMID 41279360, 2025). "We will then concentrate on the CDK4/6 inhibitors preclinical and clinical development that now are approved for the treatment of different types of cancers, alone or in combination with other drugs." (PMID 39800748, 2025). "In this review, we describe the status of CDK4/6 inhibition in cancer treatment, focusing on mechanisms by which drug resistance develops and recent progress in combination therapies." (PMID 40563591, 2025). "Remarkably, the production of SASP-related molecules triggered by CDK4/6 inhibitors enhances cancer cell proliferation, migration, invasion and immunosuppressive responses." (PMID 41388212, 2025). "CDK4/6 inhibitors have traditionally been viewed as incapable of inducing cancer cell apoptosis on their own." (PMID 40563591, 2025).